BDNF (brain derived neurotrophic factor)
Diseases named in the same sentence as BDNF in open-access papers (continued):
Sharing a sentence is not in itself a finding about the gene and the disease.
Huntington disease (continued). "This article discussed the neurobiology of brain-derived neurotrophic factor (BDNF) in Huntington's disease." (PMID 40123457, 2025). "The synthesis of BDNF is affected by wild-type Huntington in normal and Huntington disease individuals." (PMID 37287291, 2024). "ALS and Huntington's disease, involve BDNF, which contributes to motor neuron degeneration and striatal atrophy." (PMID 39568824, 2024). "Converging evidence suggests that deficits in BDNF signaling contribute to the pathogenesis of several major diseases with cognitive disorders, such as AD, Huntington disease (HD), and depression." (PMID 36850004, 2023). "This study supports the utility of this fundamental culture system, which can be easily adapted to evaluate potential therapeutics or enhance the application of therapeutic BDNF resupply strategies for Huntington’s disease or other neurodegenerative diseases." (PMID 36829435, 2023). "Boosting trophic support to striatal neurons by increasing levels of brain-derived neurotrophic factor (BDNF) has been considered as a target for therapeutic intervention for several neurodegenerative diseases, including Huntington’s disease (HD)." (PMID 36829435, 2023). "We next examined the relationship between cognitive function and five genetic polymorphisms linked to genes known to affect cognitive function in Huntington’s disease: MSH3, FAN1, MAPT, BDNF and COMT." (PMID 36519153, 2022). "In order to circumvent these problems, the modulation of BDNF has shown some success in alleviating symptoms in several studies in Huntington’s disease preclinical models." (PMID 35743271, 2022). "Several studies have investigated the probable mechanisms of the reduced BDNF levels seen in Huntington’s disease." (PMID 35743271, 2022). "The search terms included: “BDNF”, “neurodegenerative diseases”, “Alzheimer’s disease”, “Parkinson’s disease”, “Huntington’s disease”, and “amyotrophic lateral sclerosis”." (PMID 35743271, 2022). "In terms of genetic polymorphisms, we selected common polymorphisms that have been previously associated with cognitive function in Huntington’s disease [COMT, brain-derived neurotrophic factor (BDNF), FAN1, MSH3 and MAPT]." (PMID 36519153, 2022). "The pathogenesis of Huntington’s disease involved low BDNF expression, potentially mediated by the cAMP, MAPK, and Ras signaling pathways." (PMID 35743271, 2022). "The preclinical studies on BDNF modulation offer some cause for optimism, albeit cautious, for the therapeutic potential of BDNF in Huntington’s disease." (PMID 35743271, 2022). "Disruption in the axonal BDNF transport to the striatum from reduced cortical supply results in the degeneration of striatal neurons, a pathological feature of Huntington’s disease." (PMID 35625880, 2022). "Cumulative evidence has demonstrated that BDNF-expressing MSCs can confer neuroprotection, promoting functional recovery in rodent models of Huntington’s disease (HD)." (PMID 35626701, 2022). "Huntington’s disease patients exhibited moderately increased intra-platelet BDNF levels and significantly reduced cognitive/emotional abilities, suggesting that platelet BDNF did not specifically underlie psychosocial deficits in stage II Huntington’s disease." (PMID 35743271, 2022). "In this review, we present recent updates on the role of BDNF and its downstream signaling pathways in neurodegenerative diseases, including Alzheimer’s disease, Parkinson’s disease, Huntington’s disease, and ALS." (PMID 35743271, 2022). "In support of this view, reduced levels of BDNF are detected in the striata, brainstem regions, and prefrontal cortexes of Huntington’s disease cell cultures, animal models, and patients." (PMID 35743271, 2022). "In animal models of Huntington’s disease, restoring cortical expression, axonal transport, and BDNF release in the striatum promotes neuronal survival and improves behavioral phenotypes." (PMID 35743271, 2022).
Huntington disease (continued). "BDNF function is reduced in Huntington’s disease (HD), possibly because mutant huntingtin impairs its cortico-striatal transport, contributing to striatal neurodegeneration." (PMID 33568689, 2021). "Hdac4 knock-down in a mouse model of Huntington’s disease was found to delay cytoplasmic aggregates formation, restore BDNF transcript levels, and rescue neuronal and synaptic functions." (PMID 34445342, 2021). "Neurotrophins, such as brain‐derived neurotrophic factor (BDNF), are essential regulators of neuronal survival and lower level of them are related to etiology of Alzheimer's and Huntington's diseases." (PMID 33528912, 2021). "The aim of this study is to determine the molecular functions of brain derived neurotrophic factor (BDNF) in Huntington’s disease (HD)." (PMID 33631722, 2021). "This is important for the secretion of brain-derived neurotrophic factor (BDNF)—and possibly other proteins—from the Golgi and has implications on Huntington’s disease, where the process is impaired due to decreased DNAJB2b levels." (PMID 32093037, 2020). "Next, the genetic elimination of TG2 in Huntington’s disease (HD) mice models ameliorated the symptoms and restored the message and protein levels of brain-derived neurotrophic factor (BDNF)." (PMID 32717806, 2020). "BDNF overexpression prevents the decrease of VGLUT1 expression and loss of glutamatergic synapses in a mouse model of Huntington’s disease." (PMID 32219700, 2020). "Neurotrophic factors such as glial cell line-derived neurotrophic factor (GDNF), brain-derived neurotrophic factor (BDNF), and neurturin, for example, all appear to protect against the striatonigral degeneration in Huntington’s disease." (PMID 30524706, 2018). "Alterations of the neurotrophin Brain-derived neurotrophic factor (BDNF) are thought to be relevant for the neurodegeneration observed in Huntington’s disease." (PMID 29415038, 2018). "The effect of this SNP on DNAL1 is particularly interesting, as this gene is not only part of the Kyoto Encyclopedia of Genes and Genomes (KEGG) Huntington’s disease gene pathway but is also directly involved in aberrant BDNF transport." (PMID 29932126, 2018). "This study assessed how BDNF (brain-derived neurotrophic factor) and other genes involved in its signaling influence brain structure and clinical functioning in pre-diagnosis Huntington’s disease (HD)." (PMID 29932126, 2018). "When HTT gets mutated in Huntington disease, this activity of HTT also disappears and production of BDNF decreases." (PMID 27875990, 2016). "Along these lines, a recent report demonstrated changes in the BDNF expression prior to onset of motor behavior abnormalities in Huntington’s disease model mice." (PMID 26042808, 2015). "Osmotic pump infusion was previously used successfully for delivery of various trophic factors: Among others, brain-derived neurotrophic factor was applied intraventricularly in a mouse model of Huntington's disease and to the cochlea of deafened guinea pigs." (PMID 25470280, 2014). "The striatal medium spiny neuron is supported by cortically-derived brain derived neurotrophic factor and is the most vulnerable neuron in Huntington’s disease, in which growth factor and histone deacetylase activity are both disrupted." (PMID 24204683, 2013). "On the other hand, reduced delivery of BDNF leads to vulnerability in GABAergic medium spiny neurons in the caudate and putamen in Huntington’s diseases, and eventually induces age-related degeneration of these neurons." (PMID 23840814, 2013). "For instance, a significant drop in the BDNF levels in the striatum has resulted in clinical manifestations of Huntington’s disease." (PMID 24300402, 2013).
Huntington disease (continued). "Brain-Derived Neurotrophic Factor (BDNF) is the main candidate for neuroprotective therapy for Huntington's disease (HD), but its conditional administration is one of its most challenging problems." (PMID 21985529, 2011). "Reduced Brain-Derived Neurotrophic Factor (BDNF) levels have been described in a number of patho-physiological conditions, most notably, in Huntington's disease (HD), a progressive neurodegenerative disorder." (PMID 21857974, 2011). "Alterations in BDNF brain levels and activity have been described in various neurodegenerative disorders, most notably Huntington's disease (HD)." (PMID 20109193, 2010). "Recent evidence suggests that brain-derived neurotrophic factor (BDNF) is an attractive candidate for modifying age at onset (AO) in Huntington disease (HD)." (PMID 17096834, 2006). "Conclusive evidence indicates that brain-derived neurotrophic factor (BDNF) plays a pivotal role in the pathophysiology of Huntington disease (HD)." (PMID 17096834, 2006). "Cellular injury, stress, or signaling pathway alterations can disrupt the balance of BDNF/proBDNF, which may be involved in apoptotic-related neurodegenerative diseases like Alzheimer’s, Parkinson’s, and Huntington’s diseases." (PMID 40430064, 2025). "Another study discovered that BDNF and TrkB overexpression could prevent Huntington’s disease-mediated apoptosis in striatal cells by delaying caspase-3 activation via Akt and ERK survival pathways." (PMID 40430064, 2025). "In addition, the impact of experimental manipulation of BDNF levels and its pharmaceutical potential for Huntington's disease treatment are explicitly reviewed." (PMID 40123457, 2025). "For example, the impaired BDNF secretion observed in Huntington’s disease and Alzheimer’s disease may also be due to functional defects in the myosins associated with BDNF-containing secretory granules." (PMID 41254423, 2025). "Similarly, it has been demonstrated that changed neurotrophic support by BDNF/TrkB is involved in the pathogenesis of Huntington’s disease (HD), which exhibits significant neurodegeneration, particularly in the striatum and cortex." (PMID 40005159, 2025). "Furthermore, BDNF and TrkB mRNA and/or protein levels are markedly reduced in the cortex, striatum, and hippocampus of Huntington’s disease patients and mouse models." (PMID 38397748, 2024). "Interestingly, BDNF is overexpressed in R6/1 mice using the same BDNF/aCaMKII promoter construct, a model for Huntington’s disease, and BDNF-transgenes were essentially found to be devoid of pathological phenotypes." (PMID 39204102, 2024). "Deficits in neurotrophic support by BDNF have been hypothesized to contribute to the neurodegeneration of striatal neurons in Huntington’s disease (HD)." (PMID 36829435, 2023). "Similarly, studies on the pathophysiology of Huntington’s disease (HD) have shown that BDNF synthesis and transport in corticostriatal projection neurons is essential for the proper functioning of motor circuits." (PMID 37887070, 2023). "Furthermore, DNA methylation at the BDNF promoter IV in the blood of Huntington’s disease patients has been reported to increase." (PMID 35743271, 2022). "However, inconsistent changes have been reported in the peripheral BDNF levels of Huntington’s disease patients." (PMID 35743271, 2022). "Restoring striatal BDNF levels or activating downstream signaling pathways may afford therapeutic potential in the treatment of Huntington’s disease and overcoming the functional deficits experienced by its patients." (PMID 35743271, 2022). "Low levels of BDNF protein have been shown to have a role in the development of neurodegenerative disorders, such as Parkinson’s disease (PD), multiple sclerosis (MS), and Huntington’s disease." (PMID 35625880, 2022).
Huntington disease (continued). "For instance, benefits of EE on the improvement of behavioral impairments such as motor performance, depressive-like behavior, as well as defects in BDNF expression in the hippocampus and striatum in mice models of Huntington’s disease have been effectively shown." (PMID 33503967, 2021). "Although wild type huntingtin protein can interact with REST/NRSF and increase BDNF expression, mutant huntingtin, which has been found in Huntington’s disease patients, loses the ability to interact with REST/NRSF, resulting in repression of Bdnf and other REST/NRSF target genes." (PMID 34977362, 2021). "However, the alterations in corticostriatal BDNF signaling that are found in various movement disorders, such as Huntington's disease and dystonia likely constitute important pathophysiological processes of these conditions." (PMID 32651187, 2020). "BDNF plays a critical role in neuronal survival in Huntington’s Disease." (PMID 32518252, 2020). "Furthermore, it was shown that in Huntington’s disease patients’ neurons, the retrograde transport of NTRK2, and therefore BDNF signaling, is impaired by mutated HTT." (PMID 32151030, 2020). "Furthermore, downregulation of BDNF has been reported to be involved in the pathogenesis of mental disorders and neurodegenerative diseases, including AD, PD, and Huntington disease (HD)." (PMID 30463271, 2018). "Thus, the relationship between Kir4.1 channel deficits and BDNF expression in astrocytes remains controversial in Huntington’s disease." (PMID 30356026, 2018). "BDNF is widely expressed in the CNS, and its expression is decreased in several neurodegenerative diseases as demonstrated by post-mortem studies, including in AD, PD, and Huntington’s disease (HD)." (PMID 29896439, 2018). "The MSCs can be genetically modified to overexpress brain-derived neurotrophic factor (BDNF), which is one of the major trophic factors that is downregulated in Huntington’s disease (HD), a neurodegenerative disorder characterized by loss of medium spiny neurons in the striatum." (PMID 26848657, 2016). "The inhibition of the Histone Deacetylase 6 (HDAC6) increases tubulin acetylation, thus stimulating intracellular vesicle trafficking and brain-derived neurotrophic factor (BDNF) release, that is, cellular processes markedly reduced in Huntington’s disease (HD)." (PMID 26445700, 2015). "Indeed, targeted delivery of neurogenic cargo, e.g., noggin and brain derived neurotrophic factor (BDNF) packaged in AAV4 has shown long-term rescue of mouse models of severely debilitating CNS disorders like Huntington’s disease." (PMID 25285067, 2014). "Furthermore, in a mouse model of Huntington's disease characterized by striatal degeneration and deterioration in motor behavior, the impaired production of BDNF contributes to striatal degeneration and progressive motor abnormalities." (PMID 24910599, 2014). "For example, as it is known that BDNF administration can recruit new interneurons from precursor cells in the SVZ in experimental models of Huntington's disease, it is reasonable to speculate that GDAsBMP might have similar effects in 6-OHDA-induced lesions." (PMID 24477866, 2014). "Brain-Derived Neurotrophic Factor (BDNF) is a secretory protein that is widely distributed in the human brain with its expression reduced in neurodegenerative disorders including Alzheimer's and Huntington's disease." (PMID 24244264, 2013). "The crucial role of adenosine A2ARs in the maintenance of synaptic functions and BDNF levels will be reviewed here and discussed in the light of possible implications for Huntington's disease therapy, in which a joint impairment of BDNF and A2ARs seems to play a pathogenetic role." (PMID 20842321, 2010). "In addition to axonal transport of BDNF, transcription of the BDNF gene was also reported deregulated in Huntington's disease." (PMID 20507609, 2010).
Huntington disease (continued). "In stem cell-derived neural paradigms from Huntington’s disease (HD) patients alongside in vivo murine models with striatal lesions, X5050 has been illustrated to restore neuronal gene expression by enhancing the expression of key neuronal genes, notably brain-derived neurotrophic factor (BDNF)." (PMID 41252060, 2025). "Considering this, GDNF and CDNF could be of particular interest for PD, NGF could be of particular interest for AD, and BDNF, because of its rich expression in the brain, could provide support for AD, PD, spinal cord injury, multiple sclerosis (MS), and Huntington’s disease (HD)." (PMID 37047292, 2023). "Evidence also exists that BDNF is critical for the survival of striatal neurons in animal models of Huntington’s disease; therefore, repeated treatment with CBD, through BDNF up-regulation, may represent a potential strategy to rescue, at least partially, striatal neurons from degeneration." (PMID 36009400, 2022). "The delivery of BDNF may therefore be a useful treatment strategy for Huntington’s disease." (PMID 34768699, 2021). "We previously demonstrated that brain-derived neurotrophic factor (BDNF) exerts protective effects on whole brain primary cultured rat astrocytes treated with 3-nitropropionic acid (3NP), a mitochondrial toxin widely used as an in vitro model of Huntington’s disease (HD)." (PMID 33023623, 2020). "In addition, the inhibition of PDE10A (the striatal-specific PDE) in a mouse model of Huntington’s disease resulted in significant amelioration in striatal cell survival, elevated levels of BDNF and phosphorylated CREB, as well as improvement in rotarod performance." (PMID 28753652, 2017). "Studies have shown that BDNF can bind to tropomyosin receptor kinase B and activate the PI3K/Akt pathway, thereby avoiding the onset of Huntington’s disease." (PMID 39937424, 2025). "In Alzheimer’s disease (AD), Parkinson’s disease (PD), and Huntington’s disease (HD), the modulation of neuronal apoptosis and survival through the BDNF/proBDNF axis shows both conserved and context-specific patterns." (PMID 40430064, 2025). "The transcription, synthesis, intracellular transport and activity-dependent release of brain-derived neurotrophic factor (BDNF) are all impaired in a number of neurological disorders, including RTT and Huntington's disease." (PMID 38785269, 2024). "BDNF-mCherry overexpression reversed the caspase-3 activation, increased the AKT phosphorylation, and enhanced the activation of ERK observed in Huntington’s disease cells." (PMID 35743271, 2022). "In Huntington's disease, excessive pathological activity of NRSF/REST inhibits the expression of BDNF and results in neurodegeneration." (PMID 35850767, 2022). "Huntington’s disease is associated with low levels of the REST target BDNF (brain derived neurotrophic factor), and restoration of BDNF can effectively reverse the Huntington’s disease phenotype, suggesting Sirt1 and REST may exacerbate the disease by downregulation of BDNF." (PMID 33813634, 2021). "The study undertaken on a rat model of Huntington disease indicated that exposure to ELF-MF (60 Hz 0.7 mT 2 h in the morning and 2 h in the afternoon for 21 days) significantly elevated BDNF level in the rats with induced Huntington disease." (PMID 33572550, 2021). "In a mouse model of Huntington’s disease (HD), IN PACAP was able to promote expression of hippocampal BDNF and decrease the formation of mutant huntingtin aggregates." (PMID 33233734, 2020).